CALR (calreticulin)
Diseases named in the same sentence as CALR in open-access papers (continued):
Sharing a sentence is not in itself a finding about the gene and the disease.
tumor (continued). "Then, the ability to induce immunogenic cell death was measured after 72 h by detecting calreticulin (CalR) on the tumor cells’ surface." (PMID 34063457, 2021). "Previous studies have shown that CALR can participate in several aspects of tumor immune regulation." (PMID 34910788, 2021). "ROS-mediated ferroptosis promotes the translocation of calreticulin (CRT), a soluble ER-associated chaperone, on the surface of tumor cells." (PMID 33540645, 2021). "It was unexpected that whole-genome proteomics analyses predicted Hsp90ab1, calreticulin and Ppib as tumor suppressors since they are highly expressed in many cancer tissues." (PMID 33859739, 2021). "On the other hand, the administration of whole tumor cell vaccines composed of CT26 cells killed by incubation with anthracycline drugs generates tumor protection and phagocytosis by dendritic cells in a calreticulin-dependent manner." (PMID 33623783, 2021). "First, the expression of calreticulin should be assessed in larger and well-defined, homogeneous (i.e., tumor type, tumor stage, treatment) patient populations." (PMID 33920544, 2021). "Expose to wildtype CALR in cancer cells enhances the DC efferocytosis of cancer cells, which triggers the activation of immune responses in the tumor microenvironment." (PMID 34660305, 2021). "To further investigate the relationship between CALR expression and tumor prognosis, we used the Kaplan-Meier Plotter to study the correlation between CALR and relapse-free survival (RFS)." (PMID 34910788, 2021). "Calreticulin present on outer membrane of tumor cells not only stimulates their phagocytosis by APCs, but also activates the adaptive immune response, thus it is believed to be crucial for surveillance against tumors." (PMID 33440842, 2021). "Doxorubicin mediates immunogenic cell death by translocating calreticulin from the cytoplasm to the cell surface, stimulating phagocytosis of tumor cells by dendritic cells." (PMID 33401528, 2021). "Sublethal irradiated tumor cells increase their calreticulin expression while radiation induces the translocation of calreticulin from the endoplasmic reticulum to the cell surface." (PMID 34768644, 2021). "In contrast, in the irradiated tumors on the left flank of mice treated with PLP + PDT, tumor expression of calreticulin was reduced and clustered in certain regions of the tumor." (PMID 36405502, 2021). "The expression of CALR increases with tumor progression in bladder urothelial carcinoma (BLCA), breast invasive carcinoma (BRCA) and kidney renal clear cell carcinoma (KIRC)." (PMID 34910788, 2021). "Recent studies have shown that CALR is involved in the occurrence, proliferation, migration and adhesion of the tumor, and mediates cell phagocytosis, signal transduction and immune cell death (ICD)." (PMID 34910788, 2021). "The translocation of calreticulin on cell membrane sends the important ‘eat me’ danger signal and induces clearance of tumor cells by antigen presenting cells(APC), such as dendritic cells(DCs) and phagocytic cells." (PMID 34621270, 2021). "Blockade or knockdown of CALR suppresses the phagocytosis of anthracycline-treated tumor cells by DCs and abolishes their immunogenicity." (PMID 34660305, 2021). "This serves as a signal to activate macrophages and DCs, which internalize calreticulin-expressing tumor cells." (PMID 33430362, 2021). "Whole slide tumor images revealed that in tumors of control mice treated with PBS, PLP, or PBS + laser, calreticulin expression was high and uniformly expressed throughout the tumor." (PMID 36405502, 2021). "Our research suggests that CALR can be used as a biomarker to predict tumor prognosis and a potential target for tumor molecules and immunotherapy in specific tumors, which has the value for further deepen research." (PMID 34910788, 2021).
tumor (continued). "In stressed or dying cells, calreticulin exposed on the cell surface serves as a phagocytic signal to DCs, resulting in the engulfment of cancer material by DCs and in tumor antigen presentation and anticancer cytotoxic T lymphocyte-specific responses." (PMID 33920544, 2021). "In vitro experiments showed that anthracyclines promote ICD in tumor cells by inducing the translocation of calreticulin, HSP70 and 90 to the cell surface and promoting HMGB1 release." (PMID 34025657, 2021). "We further performed an immunohistochemistry experiment to validate the expression pattern of CALR between tumor and normal samples." (PMID 34868055, 2021). "Numerous preclinical studies have already shown that radio- and chemotherapy can result in higher expression levels of CALR on the tumor cell surface, resulting in enhanced anti-tumor immune responses." (PMID 34944879, 2021). "Higher ADAR1 and CALR expression was distinctly detected in peritoneal metastasis than primary tumor tissues." (PMID 35003354, 2021). "The results showed that tumor tissue significantly increased the surface expression of calreticulin and ATP and HMGB1 concentrations at 24 h after the mice treated with QD-RGD- or QD-Cat-RGD-based RT, which was consistent with the in vitro results." (PMID 34887404, 2021). "GEM demonstrated an ability to induce the cell surface expression of Calreticulin on PANC-1 tumour cell lines." (PMID 32661823, 2021). "Positive CALR staining was observed in the majority of tumor case (96%) of the oral cavity, whereas the incidence was lower in non-cancerous matching tissue cases (32%)." (PMID 34580365, 2021). "If available the ICD-related consequences of calreticulin expression or other mechanisms influencing tumor cells have been also described." (PMID 33440842, 2021). "During ICD, calreticulin (a significant marker of ICD) can migrate from the endoplasmic reticulum of tumor cells to the plasma membrane and induce dendritic cells to engulf dying tumor cells and their debris." (PMID 34041494, 2021). "Whole-genome proteomics analysis predicted the tumor-suppressing action of Hsp90ab1, calreticulin and peptidylprolyl isomerase B (Ppib)." (PMID 33859739, 2021). "The protein level of CALR gene was significantly overexpressed in tumor tissues compared to normal tissues based on HPA database." (PMID 34633991, 2021). "Tumor cell surface expression of calreticulin was significantly increased in samples resected from patients with renal cell carcinoma treated with stereotactic body radiation therapy (SBRT) (N = 14) compared to control samples (N = 16)." (PMID 33920544, 2021). "In the case of calreticulin, although this is a surface marker on dying tumor cells, it also comes to the surface in cytotoxic lymphocytes or NK cells when they release their granules to kill other cells." (PMID 33777767, 2021). "The timepoint at which calreticulin is examined as well as the tumor model investigated can affect calreticulin expression." (PMID 36405502, 2021). "In conclusion, CALR can be used as a biomarker for predicting prognosis and a potential target for tumor molecular and immunotherapy." (PMID 34910788, 2021). "Many human cancer cells have the eat-me signal calreticulin on the surface (possibly due to ER stress, or possibly a tumour suppressor mechanism), but overexpress the don’t-eat-me signal CD47 to prevent host phagocytes from phagocytosing the cancer cells." (PMID 34177884, 2021). "As a potential target for tumor therapy, few studies have comprehensively analyzed the role of CALR in cancers." (PMID 34910788, 2021). "A body of evidences showed that CALR is highly expressed in tumor cells and transported onto cell membrane to serve as a C1q receptor and prophagocytic signal for macrophage phagocytosis of cancer cells and dead cells." (PMID 32082309, 2020).
tumor (continued). "In vivo studies showed a remarkable increase in ICD manifest as an increase in both NK and activated CD8 and CD4 T cells in tumor tissues as well as calreticulin translocation." (PMID 33260534, 2020). "So, in a model of gastric cancer, calreticulin knockdown with siRNA suppressed TGF-β1-induced EMT in the tumor cells as well as impairing their migration, invasion, and metastasis formation in vivo." (PMID 32268506, 2020). "Vaccination with JAK2-mutant- and CALR-mutant-derived peptides will probably induce tumor-specific immune responses that will be further enhanced by co-vaccination with anti-regulatory epitopes, such as PD-L1- and ARG1-derived epitopes." (PMID 32630667, 2020). "First of all, early translocation of endoplasmic calreticulin to the tumor cell surface generates an “eat-me” signal for DC phagocytosis and tumor antigen uptake." (PMID 32947882, 2020). "Tumor cells undergoing ICD secrete distress signals through molecules called damage-associated molecular patterns (DAMPs), including calreticulin (CRT), adenosine triphosphate (ATP) and high-mobility group box 1 (HMGB1), to activate the immune response." (PMID 32317755, 2020). "Subsequent studies demonstrated the presence of other chaperones including HSP90, GRP96, HSP40, and calreticulin on tumor cell membranes." (PMID 32443761, 2020). "Conversely, aged or damaged cells and tumor cells often express the pro-phagocytic “eat me” ligands phosphatidylserine and calreticulin, with the balance of these opposing forces determining the activity of directly engaged phagocytic cells." (PMID 35582455, 2020). "Interaction between the activated DC and CALR at the surface of the dying tumor cell triggers its phagocytosis, thereby promoting tumor antigen uptake by the DC." (PMID 33281620, 2020). "The intracellular Ca2+ in cancer cells accompanying calreticulin release in HT29 CRC was also likely to promote apoptotic tumor damage." (PMID 32872532, 2020). "Calreticulin is a protein that can serve as an “eat me” signal, stimulating the engulfment of dying tumour cells and their apoptotic debris by macrophages and immature DCs." (PMID 33008040, 2020). "In vivo studies were also performed, showing larger amounts of ATP secretion and calreticulin translocation in tumor tissue from the treatment group as well as higher concentrations of TNF-α and IFN-γ in serum taken from treated mice." (PMID 33260534, 2020). "Recent research has demonstrated the important role of CALR in anti-tumor activity by increasing dendritic cell maturation, tumor antigen presentation and priming of CD8+ cells." (PMID 32082309, 2020). "CALR facilitates dendritic cell recognition of neoplasm antigens, which ultimately induces an antitumor immune response and results in suppression of tumor growth via cytotoxic CD8+ T cells." (PMID 32606370, 2020). "Because CALR can induce dendritic cell maturation, increasing antigen internalization and presentation, the biological function is beneficial for CALR in tumor growth control." (PMID 32082309, 2020). "Calreticulin (CALR) has anti-tumor effects by increasing dendritic cell maturation and tumor antigen presentation." (PMID 32082309, 2020). "In vivo studies also confirmed ICD via the increase in calreticulin translocation and the increase in T cell infiltration and DC maturation in the tumor." (PMID 33260534, 2020). "Recently, immune checkpoint blockade represents a breakthrough for cancer treatment, whereas immunogenic cell death, which includes CALR exposure, is also an important process in tumor immunotherapy." (PMID 32508042, 2020). "Ecto-CALR exposure on the membrane of (dying) tumor cells is important for recognition and engulfment by DCs, leading to optimal antigen presentation to T cells, hence activating an adaptive anti-tumor immune response." (PMID 32560232, 2020). "It seems likely that patients with CALR-mutant MPN have developed disease because of tumor immune escape." (PMID 32630667, 2020).
tumor (continued). "The oxidative stress induced by the Fenton reaction leads to the exposure of calreticulin on tumor cells, which leads to dendritic cells maturation and the infiltration of cytotoxic T lymphocytes in tumor." (PMID 32686685, 2020). "Recent study showed that calreticulin (CALR) is critically involved in anti-tumor activity in tumor animal models." (PMID 32082309, 2020). "It was reported that CALR-exposed dendritic cells had increased maturation status in the responses to living tumor cells, apoptotic cells and cell debris." (PMID 32082309, 2020). "Literature studies show that cisplatin has activity in multiple tumor types, and platinum agents have the ability to induce immunologic cell death in part by release of calreticulin." (PMID 32599852, 2020). "GRPs, TRAP1, protein disulfide isomerases, and calreticulin are involved in oncogenesis and promote tumor resistance to therapeutics." (PMID 32268506, 2020). "Here, calreticulin triggers the phagocytosis of dying tumor cells by dendritic cells and the subsequent expansion of autologous CD8+T-lymphocytes with anti-tumor activity." (PMID 32155954, 2020). "Therapeutic vaccination with arginase or PD-L1 therefore offers a novel way to directly affect immune inhibitory pathways, potentially altering tolerance to tumor antigens like mutant CALR and mutant JAK2." (PMID 32630667, 2020). "These tumor cells produce stress-induced ligands (DAMPs): CALR, ATP, ANXA1, and HMGB1, whose activation is conditioned by several constraints." (PMID 33281620, 2020). "Calreticulin triggers the phagocytosis of the irradiated tumor cells by dendritic cells and increases the lysis of the irradiated tumor cells by cytotoxic lymphocytes." (PMID 33297519, 2020). "Cells in tumors treated with gels containing Dox-iRGD and CpG showed enhanced cell-surface expression of calreticulin compared to tumors treated with gels containing Dox-iRGD alone or untreated tumors, indicating increased immunogenic death of tumor cells." (PMID 33173046, 2020). "Because the exposed CALR can be released into extracellular milieu, the serum CALR is highly elevated in the tumor patients and positively correlated to the prognosis of tumor." (PMID 32082309, 2020). "As such, the treatment of MPN with IFN-α probably partially reinstates otherwise-defective tumor immune surveillance, as IFN-α can induce a complete hematological response and significantly reduce both the JAK2-mutated and CALR-mutated allele burden." (PMID 32630667, 2020). "In several tumor cell lines, major mediators of anticancer immunity were identified using our treatment regimens, all above calreticulin." (PMID 30679720, 2019). "As documented in numerous in vitro and in vivo models, ecto-CALR serves as a signal to facilitate the engulfment of tumor cells by DCs, which leads to tumor antigen presentation and stimulation tumor-specific cytotoxic T lymphocytes responses." (PMID 31747968, 2019). "Of interest, that it has been previously found that IL-6 is necessary for calreticulin mediated priming of Th17 cells and inhibiting the generation of Treg cells and Th17 cells play an important role in establishing of anti-tumor immunity." (PMID 31842994, 2019). "Second, when Pgp is abundant on the tumor cell plasma-membrane, it impairs the immune-activating functions of calreticulin, hampering the tumor cell phagocytosis mediated by DCs." (PMID 31117237, 2019). "Anthracyclines induce ICD, resulting in exposure of calreticulin on the surface of tumor cells, tumor secretion of high mobility group box 1 and activation of NLR Family Pyrin Domain Containing 3 (NLRP3) inflammasome in DC." (PMID 30979057, 2019). "We also performed immunofluorescence staining for M1 TAM activation markers‐CD80 and iNos and eat‐me receptor calreticulin on tumor cells." (PMID 31376208, 2019).
tumor (continued). "A study on glioblastoma multiforme cell lines (GL261) in xenotransplant models showed that the infection of tumor cells with NDV leads to the elevated level of cell surface calreticulin as well as the increased secretion of HMGB1 and PMEL17 tumor antigens." (PMID 31217023, 2019). "This was likely further potentiated by the induction of immunogenic cell death, as indicated by increased tumor cell surface calreticulin." (PMID 31921384, 2019). "As we observed a positive correlation between CALR levels and tumor infiltration by diverse immune cell subsets, we next evaluated the global immunological profile of the TME of CALRLo versus CALRHi PT samples from Study Group 1 by IHC." (PMID 31747968, 2019). "For example, ATP attracts DCs into the tumor and the cell surface exposure of calreticulin, which is an endoplasmic reticulum-resident protein, promotes phagocytosis of irradiated tumor cells." (PMID 30941308, 2019). "These activate local DCs and induce the translocation of calreticulin, a calcium-sensor residing within endoplasmic reticulum onto the tumor cell surface." (PMID 31117237, 2019). "Using calreticulin exposed on the surface of tumor cells, which operates as an “eat me” signal to stimulate uptake of tumor antigens by APCs, we showed that the combination treatment increased this hallmark of immunogenic cell death." (PMID 31921384, 2019). "We first confirmed the selectivity of cell death induced by PKBH1 in tumor L5178Y-R cells and observed that calreticulin exposure increased when cell death increased." (PMID 31275386, 2019). "We found increased calreticulin staining on the cell surface of MNNG/HOS tumor cells undergoing doxorubicin or combination treatment compared to PBS‐treated or CD47 mAb‐treated tumor cells (P = 0.0001)." (PMID 31376208, 2019). "RT affects dead or dying cells that release antigens like calreticulin and high-mobility group protein B1 that activates dendritic cells, which in turn activate the antigen-specific T-cells to mount tumor specific immune response." (PMID 31362708, 2019). "Cell-associated danger signals associated with ICD like calreticulin promote phagocytosis, while adjuvants such as HMGB1 or F-actin induce DC activation, tumor Ag processing and cross-presentation." (PMID 30961656, 2019). "Surface-exposed calreticulin markedly enhances the phagocytosis of tumor cells by dendritic cells (DCs) that play a crucial role in the induction and regulation of antitumor immunity." (PMID 30984181, 2019). "Here we show that Hemidesmus treatment induces tumor cell cytotoxicity characterized by surface expression of calreticulin, increased HSP70 expression and release of ATP and HMGB1." (PMID 29849952, 2018). "On the other hand, radiation induces overexpression of HSP70, HSP90 and calreticulin (CALR), which promotes anti-tumor immunity." (PMID 29702669, 2018). "Radiation-induced cell death externalises DAMPs such as HMGB1, ATP and calreticulin on the tumour cells surface and the release of ROS/RNS." (PMID 30178305, 2018). "Other reports suggest the use of the recombinant calreticulin of T. cruzi during the development of experimental breast adenocarcinoma, which reveals the presence of tumor cells to the immune system." (PMID 30266743, 2018). "PERK was demonstrated to be associated with the exposure of calreticulin in non-small-cell lung carcinoma (NSCLC) and to be positively associated with ICD and anti-tumor immunity." (PMID 30282948, 2018). "Calreticulin serves as a phagocytic signal for macrophages which engulf the dying cells and subsequently can present tumor antigens." (PMID 30692991, 2018). "The radiation-induced translocation of calreticulin would promote the uptake of irradiated tumor cells by APCs and enhance the killing effect of T cells." (PMID 30115069, 2018). "We predicted that the tumor- specific neo-epitopes generated by the mutant CALR C-terminus induce immune responses in MPN patients." (PMID 30400835, 2018).